SLC2A9 (solute carrier family 2 member 9)
Description:
High-capacity urate transporter, which may play a role in the urate reabsorption by proximal tubules. May have a residual high-affinity, low-capacity glucose and fructose transporter activity. Transports urate at rates 45- to 60-fold faster than glucose. Does not transport galactose. May mediate small uptake of adenine but not of other nucleobases.
Synonyms: GLUT9; GLUTX; URATv1; UAQTL2
Tractability: Small molecule: a structure with a bound ligand is known. Antibody: UniProt places it where antibodies can reach, with high confidence; its Gene Ontology location is reachable by antibodies, with high confidence; UniProt predicts a signal peptide or a membrane-spanning region. PROTAC: its protein half-life has been measured.
Target class: SLC superfamily of solute carriers; Electrochemical transporter; SLC02 family of hexose and sugar alcohol transporters; Transporter
Gene: Protein-coding gene on chromosome 4 (9,771,153 to 10,054,936, reverse strand). Ensembl gene ENSG00000109667.
Subcellular location: Cell membrane (Isoform 1); Basolateral cell membrane; Cell membrane (Isoform 2); Apical cell membrane
Pathways (Reactome):
Disease: Defective SLC2A9 causes hypouricemia renal 2 (RHUC2)
Transport of small molecules: Cellular hexose transport
Gene Ontology:
Molecular function: D-glucose transmembrane transporter activity; fructose transmembrane transporter activity; urate transmembrane transporter activity; carbohydrate:proton symporter activity; transmembrane transporter activity
Biological process: D-glucose transmembrane transport; fructose transmembrane transport; urate metabolic process; dehydroascorbic acid transport; hexose transmembrane transport; proton transmembrane transport; transmembrane transport; urate transport
Cellular component: apical plasma membrane; basolateral plasma membrane; plasma membrane; membrane
Genetic constraint (gnomAD): Loss-of-function variants: 36 observed, 46.53 expected, observed/expected ratio (o/e) 0.77, 90% interval 0.59 to 1.02. The upper end of that interval is the gene's LOEUF score, 1.02, which puts it in group 4 of 6, group 1 being the genes least tolerant of losing a copy. Missense variants: 667 observed, 669.57 expected, observed/expected ratio (o/e) 1, 90% interval 0.93 to 1.06. Synonymous variants: 321 observed, 276.27 expected, observed/expected ratio (o/e) 1.16, 90% interval 1.06 to 1.27.
Homologues: Orthologues: chimpanzee SLC2A9 (99% identical), guinea pig SLC2A9 (84% identical), dog SLC2A9 (81% identical), mouse Slc2a9 (81% identical), macaque SLC2A9 (79% identical), rat Slc2a9 (79% identical), pig SLC2A9 (76% identical), rabbit SLC2A9 (69% identical), tropical clawed frog slc2a9 (62% identical), Drosophila melanogaster sut1 (27% identical), Drosophila melanogaster sut2 (25% identical), Caenorhabditis elegans F13B12.2 (25% identical), and 39 more. Paralogues in human: SLC2A5 (41% identical), SLC2A7 (39% identical), SLC2A1 (36% identical), SLC2A11 (35% identical), SLC2A4 (35% identical), SLC2A3 (32% identical), SLC2A14 (32% identical), SLC2A2 (29% identical), SLC2A13 (24% identical), SLC2A6 (21% identical), SLC2A8 (21% identical), SLC2A12 (21% identical), and 1 more.
Diseases named in the same sentence as SLC2A9 in open-access papers:
SLC2A9 is named in the same sentence as 70 diseases in open-access papers, as found by Europe PMC text mining. Sharing a sentence is not in itself a finding about the gene and the disease. The quoted sentences say what the papers report.
gout (127 papers, 2008 to 2026). A condition characterized by painful swelling of the joints, which is caused by deposition of urate crystals. "Slc2a9 has been suggested to function as a fructose and uric acid transporter and is likely associated with gout and leukemia in humans." (PMID 41596666, 2026). "Missense variants in SLC2A9 have demonstrated a significant association with clinical gout across diverse populations." (PMID 40093021, 2025). "GWASs and meta-analyses have identified several genes associated with gout susceptibility, including SLC2A9, SLC22A12, and SLC22A11." (PMID 41137353, 2025). "Since hyperuricemia is the key known factor that leads to gout, many of the consistently top-associated genes, such as SLC2A9, SLC22A12, or ABCG2, are involved in urate transport." (PMID 41155224, 2025). "Genetic backgrounds also markedly drive regional disparities: the SLC2A9 gene rs734553 TT genotype prevalent in East Asian populations reduces uric acid excretion efficiency by 35%, increasing gout risk by 2.3-fold compared to other ethnic groups." (PMID 40720428, 2025). "Genetic studies have identified urate transporter variants in genes such as ABCG2 and SLC2A9 as major determinants of serum urate levels and gout risk, with several risk alleles reported to be more prevalent in East Asian populations." (PMID 41465815, 2025). "We identified 22 methylation sites associated with gout, in which multiple methylation sites on SLC2A9 and SIPA1 were regulated, thereby influencing gout disease." (PMID 38831441, 2024). "SLC2A9 rs3733591 is among polymorphisms found to be common in people with hyperurecemia and gout even though contrary results have also been published." (PMID 38689651, 2024). "Our findings revealed that in the general model, the presence of SLC2A9 rs3733591-TC + CC genotypes, compared to rs3733591-TT, along with MetS, exhibited independent associations with gout." (PMID 38689651, 2024). "Within the gene loci associated with the risk of gout identified, SLC2A9 and ABCG2 have the strongest effect on serum urate concentration in the context of complex phenotype loci." (PMID 39433541, 2024). "In our investigation, we sought to ascertain the impact of MetS and the presence of SLC2A9, a gene strongly linked to urate concentrations, on gout development in Taiwan." (PMID 38689651, 2024). "SLC2A9 rs 737267, rs6449213 and rs1014290 are associated with gout in the UK, German and Croatian populations, respectively." (PMID 35922835, 2022). "have identified that polymorphism rs734553 in the SLC2A9 gene is linked to SU levels and gout in the Polynesian population." (PMID 34986901, 2022). "Two major LD blocks relating to gout were observed in chromosome 4 which is located on the p arm and q arm; the major causal genes are SLC2A9 and ABCG2, respectively." (PMID 36221101, 2022). "A CLNK SNP (rs16869924) within the established SLC2A9 gout-associated locus was shown to increase the risk of gout in Polynesian and Chinese Tibetan individuals, genetically independent on the SLC2A9 association signal." (PMID 35813212, 2022). "They showed that the SLC2A9 rs3733591 C allele is associated with the risk of gout and tophaceous gout in these populations." (PMID 36557230, 2022). "The intronic polymorphism rs734553 (G > T) in SLC2A9 is associated with an increased risk for HU and gout resulting from a change in transporter affinity for urate." (PMID 34986901, 2022). "The Atherosclerosis Risk in Communities (ARIC) study suggested that SLC2A9 genotype and sugar-sweetened beverage consumption interact to determine gout risk." (PMID 35484537, 2022). "The effects of variants in SLC2A9 (Val253Ile, and Arg265His) are also inconsistent based on studies on gout and hyperuricemia, and further studies are required." (PMID 35813212, 2022). "Genome-wide association studies (GWASs) have been successful in identifying genetic variants that are associated with hyperuricemia or gout, including SLC2A9, ABCG2, GCKR, and SLC22A11." (PMID 35484537, 2022).
gout (continued). "Together, these findings show robust results for the performed MR analyses and support a causal effect of differential DNA methylation at SLC2A9 on serum urate levels and gout risk." (PMID 34887389, 2021). "MR analyses supported significant causal effects of some CpGs on serum urate levels and gout at SLC2A9, the strongest GWAS locus for serum urate that encodes a major urate transport protein in the kidney." (PMID 34887389, 2021). "Four CpGs at SLC2A9 have significant causal effects on serum urate levels and/or gout, and two of these partly mediate the effects of urate-associated GWAS variants." (PMID 34887389, 2021). "The strength of association of ABCG2 rs2231142 with gout in the presence of HU in European was significantly different to SLC2A9 rs11942223 (ORrisk allele = 1.85 for rs2231142 compared to ORrisk allele = 1.37 for rs11942223, PHet = 2.1E− 03)." (PMID 32164793, 2020). "SNP rs3733591 in SLC2A9 was also identified as being associated with sUA levels and gout in the Han Chinese population, but the association was only significant in females in our study." (PMID 32183743, 2020). "GLUT9 provides urate reuptake, and single-nucleotide polymorphisms (SNPs) of SLC2A9 are associated not only with hyperuricemia and gout, but also with renal hypouricemia type 2 (OMIM(Online Mendelian Inheritance in Man) # 612076)." (PMID 32759716, 2020). "Replication studies showed conflicting effects of ABCG2 and SLC2A9 polymorphisms on gout and serum urate." (PMID 33087043, 2020). "This emphasizes the strong influence of ABCG2 and SLC2A9 variants on gout development and points out the importance of identifying high risk patients having these genetic variants." (PMID 33087043, 2020). "For SLC2A9 rs11942223, the T allele associated with gout in the presence of HU in European (OR = 1.37, P = 4.7E− 06), however significantly weaker than ABCG2 rs2231142 141K (PHet = 0.0023)." (PMID 32164793, 2020). "Many more individual studies have replicated the findings of GWASs and these were summarized in systematic reviews of the effects of ABCG2 and SLC2A9 polymorphisms on gout." (PMID 33087043, 2020). "We conducted a systematic review and meta-analysis to assess associations between SNPs in ABCG2 and SLC2A9 and gout, hyperuricemia and serum urate, stratified by ethnicity." (PMID 33087043, 2020). "Observational studies in adults with any polymorphism in ABCG2 or SLC2A9, and outcome including gout, hyperuricemia, and serum urate were included for pooling." (PMID 33087043, 2020). "Our pooled results showed a trend of decreasing the risk of gout and serum urate in most SLC2A9 variants, except for the effect of rs3733591 on gout in Asians." (PMID 33087043, 2020). "We did observe an effect also for SLC2A9 rs11942223 in the gout vs HU comparison for Europeans (OR = 1.37 for risk allele); however, this was notably weaker than that for ABCG2 rs2231142 (OR = 1.85; PHet = 0.0023)." (PMID 32164793, 2020). "A larger cohort would provide a clearer view of the effects of the variants of the SLC22A12 and SLC2A9 genes on the development of hyperuricemia and gout." (PMID 32759716, 2020). "Genetic variants of this gene lead, as in the case of SLC2A9, to hyperuricemia and gout and rare cases to hypouricemia type 1 (OMIM # 220150)." (PMID 32759716, 2020). "The SLC2A9 variant is more prevalent in Eastern and Western Polynesian people compared to New Zealand European people and confers a strong risk for gout." (PMID 31718705, 2019). "Several studies have associated some non-synonymous variants of SLC2A9 gene to hyperuricemia and gout, especially rs3733591, rs6449213, rs16890979, rs1014290 and rs10489070 mostly in Caucasians, African-Americans and Asian populations." (PMID 29615104, 2018). "Associations with gout in specific joints were significant for SLC2A9 rs12498742 in wrists and midfoot joints." (PMID 30181573, 2018).
gout (continued). "Even though polymorphism rs2231142 acted as a risk factor for gout development, our study also found that polymorphism in SLC2A9 gene revealed associated effect dependent on rs2231142 genotypes." (PMID 29453348, 2018). "Variants in glucose transporter 9 (GLUT9, also referred to as URATv1), coded for by the SLC2A9 gene, are strongly associated with both hyperuricemia and gout, a finding that has been successfully replicated in multiple studies." (PMID 29904633, 2018). "For example, polymorphisms rs9999470 which regulates SLC2A9 function showed an additive significant association with gout in those with polymorphism rs2231142 genotype TT." (PMID 29453348, 2018). "Recently, common genetic variants of SLC2A9 be strongly associated with serum urate level and gout in Caucasian cohorts from Italy, UK, Croatia, the United States, Germany, and Austria." (PMID 30087870, 2018). "In summary, the known genetic associations at ABCG2 and SLC2A9 with serum urate and gout were replicated in CKD patients with higher effect sizes for ABCG2 in patients with CKD compared to individuals from the general population." (PMID 30181573, 2018). "The two lead SNPs rs3775948 and rs13129697 in SLC2A9 on chromosome 4 was associated with hyperuricemia or gout." (PMID 29558500, 2018). "Of these, 13 variants were common (MAF ≥ 5%) and located in known serum urate GWAS loci, including rs2231142 (Q141K) in ABCG2 (beta: 0.22, p = 2.4 × 10−32; OR for gout: 2.05, p = 1.7 × 10−15), and other variants in SLC2A9, ABCG2, GCKR, SLC17A1, and SLC17A414." (PMID 30315176, 2018). "In this preliminary study, we sought to determine the influence of two non-synonymous variants rs2280205 and rs2276961 of the SLC2A9 gene on the occurrence of gout in Cameroonians." (PMID 29615104, 2018). "Here, our study demonstrates that those with mutants in both ABCG2 and SLC2A9 genes cause an additive interaction effect for gout occurrence." (PMID 29453348, 2018). "Genetic associations with detailed information about the affected joint localization showed significant associations for the SLC2A9 risk allele with gout of the wrists and midfoot joints." (PMID 30181573, 2018). "A study from Aotearoa New Zealand reported that a non-synonymous SLC2A9 Arg265His variant is associated with tophi in Māori with gout." (PMID 28566086, 2017). "Variants in two genes, ABCG2 and SLC2A9, are consistently associated with hyperuricaemia and prevalent gout in many different populations." (PMID 28270222, 2017). "It is proved that the SLC2A9 variant rs3733591 served as an important genetic checkpoint for tophaceous gout and increased uric acid levels from two geographically diverse populations." (PMID 29158942, 2017). "The SLC2A9 rs11942223 risk allele is strongly associated with prevalent gout in Māori and Pacific people living in Aotearoa New Zealand." (PMID 28270222, 2017). "While the SLC2A9 gene has been most frequently associated with gout and renal disease in humans, this is the first report of SLC2A9 in connection to eyelid shape and positioning." (PMID 26098909, 2015). "Several genes including SLC2A9 possess obvious gender differences on gout risk and understanding the genetic mechanisms of female gout is equally important." (PMID 26290326, 2015). "The gout GWAS yielded disappointing results; only SLC2A9 and ABCG2 were associated at a genome-wide level of significance." (PMID 25889045, 2015). "Previously, we and others examined the SNPs SLC22A12 and SLC2A9, and their associations with gout or hyperuricemia in different Chinese populations." (PMID 24857923, 2014). "Results from a series of GWAS studies (genome-wide association scans) revealed a significant correlation between genetic variants in the gene SLC2A9 and serum UA level, the excretion fraction of UA, gout and body mass index." (PMID 25268603, 2014).
gout (continued). "Variant c.881G>A in the SLC2A9 gene was significantly associated with elevated serum uric acid concentrations and gout in the Han Chinese, Solomon Island and Japanese cohorts, but not in the Eastern Polynesians, Western Polynesians and Europeans." (PMID 24827988, 2014). "Recent results revealed significant correlations between genetic variants in SLC2A9 and serum UA levels, the excreted fraction of UA, blood pressure, body mass index and gout." (PMID 24827988, 2014). "The studies have demonstrated that genetic polymorphisms of SLC2A9, URAT1 are key regulators of urate homeostasis, the inheritance of one predisposing variant of SLC2A9 or URAT1 increases the risk of an individual’s developing gout." (PMID 23738004, 2013). "Heterogeneity (allelic and genetic) is also evident in gene associations with gout between among South East Asian, Polynesian and European Caucasian at SLC2A9 and ABCG2." (PMID 24286387, 2013). "SLC2A9 was the first urate transporter gene that was identified from GWAS and has shown the most robust association with plasma urate and gout in previous studies." (PMID 23422251, 2013). "To date, several recent genome-wide association studies (GWAS) and follow-up studies have identified genetic variants of SLC2A9 associated with urate concentrations and susceptibility to gout." (PMID 22393348, 2012). "Genetic regulators of serum urate concentration that have been previously associated with gout at a genome-wide level of significance (P < 5 × 10-8) in Caucasian samples are SLC2A9 and ABCG2." (PMID 22541845, 2012). "To date, 14 genetic variants in SLC2A9 (based on eight study populations) have been reported to be associated with gout in humans." (PMID 22393348, 2012). "This initial study was rapidly followed by six genome-wide association (GWA) studies and other analyses, which reported that genetic variants of the SLC2A9 gene were associated with serum uric acid levels and gout in other cohorts." (PMID 22393348, 2012). "Several recent genome-wide association studies (GWAS) and follow-up studies identified that genetic variants of SLC2A9 had a role in affecting urate concentrations and susceptibility to gout." (PMID 22393348, 2012). "An additional SLC2A9 variant, R265H (rs3733591), contributes significantly to the development of elevated urate concentrations and gout in Han Chinese, Solomon Island and Japanese sample sets, but not in a Caucasian sample set." (PMID 21658257, 2011). "The intronic SLC2A9 variant rs11942223 best explains the strong role that SLC2A9 played in the development of gout in NZ Māori, Pacific Island and Caucasian sample sets." (PMID 21658257, 2011). "Our results also suggest that the effect of this variant is population-specific, further confirming population heterogeneity regarding the association of SLC2A9 with gout." (PMID 21658257, 2011). "The C allele of the nonsynonymous Arg265His (rs3733591) variant of SLC2A9 confers risk for gout in Han Chinese, Solomon Island and Japanese samples, with a stronger role in tophaceous gout." (PMID 21658257, 2011). "The R265H nonsynonymous SLC2A9 variant has previously been demonstrated to be associated with gout and tophaceous gout in Han Chinese and Solomon Islanders, and it is associated with the development of gout in Japanese males." (PMID 21658257, 2011). "Given the heterogeneity evident in risk conferred for gout at SLC2A9 and ABCG2 in the Asian and Austronesian populations studied so far, further investigation of these genes in samples derived from Asian and Austronesian people is warranted." (PMID 21658257, 2011). "The strongest association signal with gout was detected for intronic SNPs rs6855911 and rs734553 in the SLC2A9 gene, which is consistent with previous studies on gout and serum UA levels." (PMID 19890391, 2009). "It is noteworthy that both SNPs located in SLC2A9 gene showed deviation from HWE in gout cases, which can in some degree support a true association." (PMID 19890391, 2009).